IL15 (interleukin 15)
Diseases named in the same sentence as IL15 in open-access papers (continued):
Sharing a sentence is not in itself a finding about the gene and the disease.
asthma (25 papers, 2008 to 2025). "IL-15 was one of the few cytokines significantly associated with autoantibodies isolated from the sputum of individuals with severe asthma and IL-15–mediated CD8+ memory T cell development is being increasingly recognized in various disease settings." (PMID 40048261, 2025). "Given that IL-15 can recruit TEMRAs into non-lymphoid tissue, induce TEMRA proliferation, and is associated with asthma exacerbations, we examined IL15 expression in airway brushings from patients with MMA and SA." (PMID 40048261, 2025). "Recently it has been shown that IL-15 deficiency increases airway resistance and decreases compliance in a mouse model of asthma." (PMID 31996218, 2020). "IL-15 deficiency in asthma exacerbations has been previously identified in bronchoalveolar lavage macrophages." (PMID 29486764, 2018). "Rhinoviruses (RVs) are the major cause of asthma exacerbations, and IL-15 levels are decreased in the airways of subjects with asthma." (PMID 24556715, 2014). "Since induction of both IFN types is deficient in asthma and related to asthma exacerbation severity, IL-15 has potential to correct deficiencies present in antiviral immunity in asthma." (PMID 21779162, 2011). "This invites the hypothesis that dysregulated expression of IL-15 may be a mediator of disease pathogenesis in SA and, more insidiously, portend the development of T1-associated diseases following the diagnosis of asthma." (PMID 40048261, 2025). "In asthma, IL-15 has been associated with regulation of eosinophil viability." (PMID 29486764, 2018). "Recent reports, all using ovalbumin have shown aggravation of asthma by pentraxin 3, prostaglandin E2, IL-15-deficiency or suppression of asthma by anti-inflammatory protein 2 from hookworms [20▪▪], natural killer (NK) receptor 1 and inhibition of hypoxia inducible factor-1α." (PMID 28346234, 2017). "IL15 has also been linked to asthma and allergy by DNA polymorphism association." (PMID 21779351, 2011). "We also investigated whether IL-15 deficiency in asthma is related to parameters of severity and virus load during experimental RV16 infection in vivo." (PMID 21779162, 2011). "As IL-15 is deficient in asthma this suggests either or both of prophylactic or therapeutic treatment approaches may have value." (PMID 21779162, 2011). "Finally, our findings of deficient IL-15 production in asthma, combined with previous reports of deficient IFN-β, IFN-λ, IFN-γ and IL-12, suggest complex impairment of anti-viral immune responses in asthma." (PMID 21779162, 2011). "This study investigating the role of IL-15 in rhinovirus infection and asthma has also major implications in other diseases, for example pandemic influenza, where asthma is a major risk factor for severe disease and death, and COPD and cystic fibrosis where IFN-β deficiency is also present." (PMID 21779162, 2011). "We hypothesised that IL-15, a cytokine implicated in innate and acquired antiviral immunity, may be deficient in asthma and important in the pathogenesis of asthma exacerbations." (PMID 21779162, 2011). "In addition, we determined whether RV induction of IL-15 ex vivo is deficient in macrophages from asthmatic subjects and whether IL-15 levels in BAL fluid are deficient in asthma." (PMID 21779162, 2011). "Deficient IL-15 production in asthma may be important in the pathogenesis of asthma exacerbations." (PMID 21779162, 2011). "Our findings add what we believe is a new dimension to understanding asthma heterogeneity, identifying IL-15 as a potential target for treatment." (PMID 40048261, 2025). "The use of an allergic asthma model with a TH2 / TH17 inflammatory component approximating asthma in humans would better reflect the effect of IL-15 in asthma." (PMID 31996218, 2020). "We verified the levels of endogenous human and mouse IL-15 after injection of the complex in wild type mice and in asthma challenged mice." (PMID 31996218, 2020).
asthma (continued). "This study shows that subjects with asthma and multiple AETRIs exhibit a pro-inflammatory PBMC transcriptome at baseline characterized by abnormalities in STAT1 and IL-15 and a dysregulated transcriptional profile during asthma exacerbations." (PMID 29486764, 2018). "Subjects with asthma and multiple AETRIs display a pro-inflammatory signature at baseline, associated with elevated STAT, IL-15 and ISGs, and an impaired STAT1 response during acute asthma exacerbations." (PMID 29486764, 2018). "Based on these previous observations and our novel finding in multiple AETRIs, the role of IL-15 in asthma appears to be context specific with different roles at baseline and during respiratory infections." (PMID 29486764, 2018). "Both IL-1α and IL-1β, for example, are known to be molecules with a strong proinflammatory role, IL-15 has been reported to be elevated in celiac patients in previous studies, and IL-5 plays an important role in the pathophysiology of asthma." (PMID 23533306, 2013). "In asthmatic subjects, there is a deficiency in rhinovirus-induced production of IL-15 by macrophages, which indicates immunodeficiency in asthma is surprisingly broad, also involving IL-15, an important cytokine that bridges innate and acquired immunity." (PMID 21779162, 2011). "We report herein the first investigation of the role of IL-15 in the pathogenesis of RV-induced asthma exacerbations." (PMID 21779162, 2011). "In an animal model of asthma overexpression of IL-15 suppresses Th2-mediated-allergic airway response via induction of CD8+ T cell-mediated Tc1 response." (PMID 18315837, 2008). "IL15 expression also positively correlated with IL15RA expression in patients with asthma, which could represent trans presentation of IL-15 by damaged airway cells." (PMID 40048261, 2025). "IL-15 is therefore a logical therapeutic target for allergic asthma, however it is noteworthy that IL-15 may play a protective role during virus-induced asthma exacerbations." (PMID 26922672, 2016). "For example, lung epithelial cells constitutively express IL-15 and IL-15Rα, and neutrophils and macrophages can be a major source of IL-15 that is produced during a variety of lung inflammatory diseases including sarcoidosis, tuberculosis, bronchitis, and asthma." (PMID 22624047, 2012). "However in another animal model of asthma blocking IL-15 prevents the induction of allergen-specific T cells and allergic airway inflammation." (PMID 18315837, 2008). "The IL-15 gene is located on chromosome 4q27, approximately distal to the IL2 gene and may be associated with an increased susceptibility to asthma." (PMID 18315837, 2008). "Finally, some authors hypothesize a shared immunological pathway due to IL-15, that is indeed involved in both asthma and CD." (PMID 33952340, 2021). "Asthma‐2 (n = 19) combined a pro‐inflammatory signature, with a Th2 and innate immune response with upstream modulators of IL‐1β, TNF, IL‐13, IL‐15, and IFNγ." (PMID 34962717, 2021). "We also show induction of IFN-β and IL-15 to be NF-kB dependent, an important finding which has implications for NF-kB inhibitor drug development programmes as these drugs have potential to worsen rather than improve asthma exacerbation severity, by further enhancing deficiencies of IL-15 and IFN-β." (PMID 21779162, 2011). "Interestingly, IL15 expression negatively correlated with the percentage predicted FEV1, a measure of airway obstruction in asthma." (PMID 40048261, 2025). "There was a significant positive correlation between IL15 expression and markers of T cells, including CD3E and CD8A but did not include CD4, suggesting the presence of nested CD8+ T cells in the airways of patients with asthma as previously observed." (PMID 40048261, 2025). "Though we did not demonstrate a therapeutic effect of the IL-15Cx in our mouse model of house dust mite-allergic asthma, other therapies implicating IL-15 in asthma should not be completely abandoned." (PMID 31996218, 2020).
asthma (continued). "In conclusion, we did not demonstrate an effect of the IL-15 / sIL-15Rα complex in our mouse model of HDM-allergic asthma on bronchial hyperreactivity, bronchial remodeling and inflammatory response." (PMID 31996218, 2020). "In addition, focusing only on the taxa that were shown to be significantly decreased within the asthma BALs, their combined relative abundance inversely correlated with BAL IL-5, IFN-γ, and IL-15 levels (n = 40)." (PMID 31836714, 2019). "IL-15 mRNA expression levels in bronchial biopsies in asthma are not increased, while protein levels in sputum are undetectable in normal subjects and steroid naïve asthmatics, but detectable in steroid-treated asthmatics." (PMID 21779162, 2011). "There is a single report that IL-15 gene expression is increased in asthma exacerbations in children but no data on IL-15 in RV infections." (PMID 21779162, 2011). "IL-15 could be involved in another type of asthma for which our model, mainly Th2 and Th17-driven, is not relevant." (PMID 31996218, 2020). "However, there are no published data on IL-15 induction in macrophages by RV, nor on its possible importance in the pathogenesis of asthma exacerbations." (PMID 21779162, 2011). "Finally, NF-κB inhibitors are in development as possible therapies for asthma exacerbations, our data that IFN-α, IFN-β and IL-15 induction by RV are all NF-κB dependent suggest that such approaches may further impair already deficient responses in asthma." (PMID 21779162, 2011). "Because signalling by IL-15 occurs via the IL-2/IL-15 receptor β-chain (CD122) and common γ chain receptor (CD132) expressed primarily by NK and memory CD8 T cells, it will be of great interest to determine the levels of these receptors on airway NK and CD8 T cells in virus-induced asthma." (PMID 21779162, 2011).
colitis (23 papers, 2008 to 2024). Inflammation of the colon. "Taking into account that IL-15-deficient mice developed severe colon inflammation despite the presence of Treg cells among the adoptively transferred CD4+ T cells, we investigated the fate of the transferred Treg cells in IL-15-deficient mice with colitis." (PMID 26964669, 2016). "To further assess the role of IL-15 in the increased susceptibility of Nlrp3−/− to DSS-induced colitis, we employed an antibody-based neutralization strategy." (PMID 27610005, 2016). "We found that the mice deficient for both IL-6 and IL-15 (IL-15koIL-6koRAG2ko) were resistant to T-cell-induced colitis in contrast to IL-15koRAG2ko mice." (PMID 26964669, 2016). "Lastly, inhibition of IL-15 signaling with a neutralizing antibody protected Nlrp3−/− from colitis, an effect that was associated with a reduction in the expression of IL-17 in colonic tissue." (PMID 27610005, 2016). "Previous studies have shown that IL-6 and IL-10 play essential roles for the maintenance of intestinal homeostasis and the prevention of colitis, while proinflammatory cytokines, such as IL-17 and IL-15 promote intestinal dysbiosis associated with increased susceptibility to colitis." (PMID 28943876, 2017). "In addition, the concentration of pro-inflammatory cytokines, in particular IFN-γ, TNF-α and IL-6 secreted by total LP cells in the colon, was two- to sixfold higher in IL-15-deficient mice with CD4+ T-cell-driven colitis compared with RAG2ko host mice." (PMID 26964669, 2016). "Furthermore, neutralizing IL-15 normalized the susceptibility of Nlrp3−/− mice to DSS-induced colitis, an effect that was associated with reduced expression of IL-17 in colonic tissues." (PMID 27610005, 2016). "Of note, previous reports show that IL-15 has a pro-inflammatory role and is highly expressed in IBD patients, as well as promotes intestinal dysbiosis and increases susceptibility to colitis." (PMID 39275347, 2024). "Consistently, IL-15 knockout mice were resistance to DSS-induced colitis, reduced NK cell population and IFN-γ level in lamina propria." (PMID 38106519, 2023). "In a mouse model of colitis, IL-15-dependent NKp46+ cells amplified intestinal inflammation via the recruitment of inflammatory monocytes." (PMID 36059513, 2022). "The secretion of IL-2, IL-7, IL-12, and IL-15 in colonic tissues from colitis mice in the DSS group was higher than that in the normal, DSS + SSP, and DSS + 5-ASA groups." (PMID 32714185, 2020). "While WT Treg cells efficiently prevented possible intestinal inflammation mediated by IL-15Rαko naive CD4+ T cells, the mice injected with IL-15-deprived Treg and WT CD4+ T cells demonstrated significant body weight loss and symptoms of colitis." (PMID 26964669, 2016). "In a murine model, IL-15 KO mice have been shown to have significantly diminished acute and chronic colitis compared to wild-type mice, further suggesting that IL-15 production is required to sustain chronic infections." (PMID 18628987, 2008). "Transgenic mice with intestinal IL-15 overexpression show distinct increase in the numbers of butyrate-producing bacteria, resulting in high susceptibility to dextran sulfate sodium (DSS)-induced colitis." (PMID 38106519, 2023). "Accompanying the modifications in Treg status in IL-15koRAG2ko mice, which develop premature colitis following CD4+ T-cell transfer, we have found that the frequency and absolute number of total CD4+ T cells were significantly higher in the colon of IL-15-deficient mice." (PMID 26964669, 2016). "G-CSF, GM-CSF, IL-6, IL-15, IP-10, KC, MIP-1α, and MIP-1β levels were increased in animals with colitis." (PMID 34916909, 2021). "Here the authors show that IL-15 promotes Foxp3 and inhibits RORγt expression in CD4 T cells, and that IL-15 is critical to suppress colitis by maintaining the Treg to Th1/Th17 ratio in a mouse model." (PMID 26964669, 2016).
colitis (continued). "The levels of GM-CSF, IL-12p70, IL-15, IL-23, and TGF-β in untreated mice with colitis were elevated compared to those of the Normal, TNBS + Curcumin, and TNBS + Mesalazine groups." (PMID 27932984, 2016). "In our study, we observed a similar reciprocal relationship between NLRP3 and IL-15, where the expression of NLRP3 protects mice from experimental colitis and its deletion leads to increased IL-15 expression and enhanced intestinal inflammation." (PMID 27610005, 2016). "Analysis of cytokines predicted to activate Ifng expressing CD4+ T cells in CPI colitis included IL2 (z score 4.7, P < 1.0 × 10−27), IL7 (z score 3.8, P < 9.8 × 10−19), IL15 (z score 3.4, P < 5.2 × 10−34), IL18 (z-score 2.0, P < 4.0 × 10−25) and IL23A (z-score 2.6, P < 2.1 × 10−31)." (PMID 37872166, 2023). "CD1d independent NK1.1+CD8+ T cells produced high levels of IFN-γ and TNFα, contributing to colitis pathogenesis, and suggested that DCs and macrophages might be responsible for increasing NK1.1+CD8+ T cells through IL-15." (PMID 35741032, 2022). "NKp46+ ILC-specific inactivation of c-FLIP leads to the loss of all IL-7/IL-15-dependent NKp46+ ILC, thereby inducing early-onset chronic colitis and subsequently microbial dysbiosis; meanwhile, the depletion of cNK, but not NKp46+ ILC1/3, aggravates experimental colitis." (PMID 32103006, 2020). "In addition, we demonstrated in vivo that Treg cells with impaired IL-15 signalling when co-transferred with WT naive CD4+T cells into RAG2ko mice failed to prevent the development of colitis, while WT Treg co-transferred with IL-15Rαko naive CD4+ T cells efficiently protected against IBD." (PMID 26964669, 2016).
HIV-1 infection (22 papers, 2009 to 2024). The type species of lentivirus and the etiologic agent of acquired immunodeficiency syndrome (AIDS). "Hu-NSG-Tg(IL-15) mice were highly susceptible to HIV-1 infection and showed a decrease in the percentage of CD4+ T cells starting at 4–5 weeks post-infection and remaining low thereafter." (PMID 36851579, 2023). "The differentiation of CCR5+CD4+ T cells is associated with the availability of IL-15, which increases during acute HIV-1 infection." (PMID 36821374, 2023). "It is plausible that the broader epigenetic reconfiguration induced by IL-15 could alter downstream ITAM signaling recovering NK cell function in HIV-1 infection, but the underlying mechanism requires further investigation." (PMID 38385747, 2024). "IL-15 also increases the susceptibility of CD4TL to HIV-1 infection." (PMID 36766808, 2023). "We conclude from these data that Hu-NSG-Tg(IL-15) mice are highly susceptible to HIV-1 infection." (PMID 36851579, 2023). "However, plasma IL-15 levels increase during HIV-1 infection and are associated with high viral load or set point, likely because of the correlation between IL-15 and the frequency of HIV-1 target cells." (PMID 36821374, 2023). "Moreover, whether these IL-15 knock-in or transgenic mouse models are susceptible to HIV-1 infection has only been demonstrated in one of these models thus far." (PMID 36851579, 2023). "Compared with untreated cells, IL-15 priming induced a higher ΔΨm in NK cell subsets in HIV-1 infection." (PMID 38385747, 2024). "IL-15 priming enhanced NK cell functionality to anti-CD16 stimulation in HIV-1 infection, representing an effective strategy for pharmacologically boosting NK cell responses." (PMID 38385747, 2024). "Elevated plasma levels of IL-15, another pro-inflammatory cytokine, have been observed in individuals with HIV-1 infection and are also correlated with higher HIV viral load due to their association with the frequency of HIV-1 target cells." (PMID 39301032, 2024). "The effects of IL-15 priming on NK cell metabolism and functionality have important implications for clinical translation in HIV-1 infection." (PMID 38385747, 2024). "This, however, raises concerns about the ability of a transgenic IL-15 humanized mouse’s ability to sustain HIV-1 infection similar to traditional humanized mice." (PMID 36851579, 2023). "Overall, our results demonstrate that IL-15 facilitates HIV-1 infection both in vitro and in humanized mice." (PMID 36821374, 2023). "Together, these studies demonstrate that human IL-15 expressing mice are able to sustain HIV-1 infection and can be used for long-term studies." (PMID 36851579, 2023). "IL-15/IL-15Rα based immunomodulatory molecules have shown a high potency to activate and increase cytotoxic activity of NK cells in the case of HIV-1 infection." (PMID 37936122, 2023). "Due to its functions in the maturation and homeostasis of memory CD8+ T cells and NK cells, IL-15 is often considered a useful immunotherapeutic agent to treat HIV-1 infection." (PMID 36821374, 2023). "Further, the activation of NK cells by N-803, an IL-15 superagonist, inhibited acute HIV-1 infection of humanized mice." (PMID 36851579, 2023). "This suggest that the mechanism by which EV-miR-155 promote HIV-1 infection is likely IL-15-dependant." (PMID 36766808, 2023). "Our study suggests that IL-15 plays confounding roles in HIV-1 infection, and future studies on the IL-15–based boosting of anti–HIV-1 immunity should carefully examine the potential effects on the expansion of HIV-1 reservoirs in CCR5+CD4+ T cells." (PMID 36821374, 2023). "To that end, we pre-treated PBMCs form patients with chronic viraemic HIV-1 infection with IL-15 alone and/or M1/Mdivi+MT overnight prior to short-term peptide stimulation with HIV-1 Gag or CMV-pp65." (PMID 35865519, 2022).